ADAM10 (ADAM metallopeptidase domain 10)
Diseases named in the same sentence as ADAM10 in open-access papers (continued):
Sharing a sentence is not in itself a finding about the gene and the disease.
reovirus infection (1 paper, 2011). "Cells harboring a disrupted ADAM10 (A Disintegrin and Metalloprotease 10) allele survived reovirus infection, and subsequently ADAM10 was shown by RNA interference to be important for replication of HIV-1." (PMID 21569301, 2011). "In this study, we identified ADAM10 by gene trap insertional mutagenesis as a disrupted gene in cells surviving cytolytic reovirus infection, and we demonstrated the importance of ADAM10 expression at a post-entry step in HIV-1 replication." (PMID 21569301, 2011).
Scott syndrome (1 paper, 2019). Scott syndrome is an extremely rare congenital hemorrhagic disorder characterized by hemorrhagic episodes due to impaired platelet coagulant activity. "Immortalized B-cells from a Scott syndrome patient were found to show the same surface expression of ADAM10 as control cells and a comparable expression of CD23." (PMID 30753537, 2019). "Calcium-dependent ADAM10 activation could not be induced in lymphocytes of patients with Scott syndrome harbouring a missense mutation in ANO6." (PMID 30753537, 2019).
scrapie (1 paper, 2011). A fatal disease of the nervous system in sheep and goats, characterized by pruritus, debility, and locomotor incoordination. "While a recent in vitro study showed no shedding-dependent modulation of prion conversion, incubation times after scrapie inoculation were prolonged in mice overexpressing Adam10." (PMID 21619641, 2011).
serous cystadenoma (1 paper, 2023). A serous neoplasm in which the cysts and papillae are lined by a single layer of cells without atypia, architectural complexity or invasion. "We identified overexpression of PURPL, underexpression of miR-363-3p, and upregulation of ADAM10 in the OSC tissues enrolled for this study, in contrast to normal ovarian tissues and serous cystadenoma tissues." (PMID 37781085, 2023).
staphylococcal infection (1 paper, 2021). An infection caused by Staphylococcus. "Consequently, it was postulated by Wilke and Wardenburg that the use of zinc metalloprotease inhibitors including ADAM10 might be useful in combating staphylococcal infections." (PMID 34684179, 2021).
staphylococcal pneumonia (1 paper, 2025). Pneumonia caused by infections with bacteria of the genus staphylococcus, usually with staphylococcus aureus. "Using a 3D human in vitro staphylococcal pneumonia model, we show that α-toxin-induced activation of ADAM10 as well as α-toxin-induced cytotoxicity leads to increased CX3CL1 release, which enhances monocyte motility and impairs intracellular killing capacity by monocytes." (PMID 41081526, 2025).
status epilepticus (1 paper, 2019). Status epilepticus is defined as a continuous seizure lasting more than 30 min, or two or more seizures without full recovery of consciousness between any of them. "Inhibition of miR-23a increased hippocampal ADAM10 expression while an increase in miR-23a suppressed hippocampal ADAM10 expression in pilocarpine-induced status epilepticus (SE) mice." (PMID 31114485, 2019).
Streptococcus pneumonia (1 paper, 2016). "Interestingly, loss of ADAM10 has also been implicated in lung epithelial injury from other bacterial pore-forming toxins, like pneumolysin from Streptococcus pneumonia." (PMID 27043625, 2016).
Tinnitus (1 paper, 2022). Tinnitus is an auditory perception that can be described as the experience of sound, in the ear or in the head, in the absence of external acoustic stimulation. "In previous gene-wide analyses, it was shown that TSPAN5 was associated to tinnitus (uncorrected p = .00187) and that there is an association of ADAM10 with cisplatin-induced ototoxicity (uncorrected p = .0466)." (PMID 36699085, 2022).
Ureteral obstruction (1 paper, 2018). Obstruction of the flow of urine through the ureter. "In vivo, Wistar rats (n = 36) were subjected to unilateral ureteral obstruction (UUO) (n = 18) or sham surgery (n = 18), with tissues from post-operative day 3, 7, and 14 days examined, and PAX2/ADAM10 activity measured." (PMID 30117015, 2018).
tumor (196 papers, 2005 to 2026). "In our clinical cohort, ADAM10 mRNA was significantly upregulated in 13 tumor tissues (p<0.05), exhibiting superior diagnostic accuracy (AUC=0.8402, CI:0.6801-1.000, p=0.0032)." (PMID 40726981, 2025). "Western blotting of anti-human ADAM10 immunoprecipitates from tumours confirmed the loss of hADAM10 expression in KO tumour cells." (PMID 41226720, 2025). "ADAM10 is reportedly over-expressed in various cancer types, where it is often associated with a more aggressive tumour phenotype and poor patient prognosis." (PMID 41226720, 2025). "The results showed that the overexpression of ADAM10 reversed the reduced tumor growth caused by circSNX5 knockdown, highlighting ADAM10’s critical involvement in circSNX5-mediated oncogenesis." (PMID 39155279, 2024). "ADAM10 is also negatively associated with tumor immunosuppression and interrelated with the immune infiltration of tumors." (PMID 39211038, 2024). "The ADAM‐10 and its genetic polymorphism had been proven to influence various diseases including neoplasms according to previous literatures." (PMID 36946281, 2023). "Prior studies have confirmed that the pro-tumor role of ADAM10 is linked to the interaction among ADAM10, EphA3, and ephrin-A5." (PMID 35551177, 2022). "A decreased ratio of PD-L1 protein to mRNA in the tumor is associated with poor prognosis and correlates with increased expression of ADAM10 and ADAM17 in a variety of malignancies." (PMID 34943606, 2021). "Increasing evidences have revealed that a disintegrin and metalloproteinase 10 (ADAM10) is implicated in tumor development." (PMID 32256208, 2020). "ADAM10 is a membrane-associated sheddase and has been involved in the proteolysis of several protein substrates and in tumor spread in several types of cancer." (PMID 32512881, 2020). "As for overall survival, T stage, regional lymph node metastasis, residual tumor, ADAM-10, and ADAM-17 were associated with decreased overall survival for patients with HC." (PMID 29776401, 2018). "This is especially important, considering that ADAM10 is also associated with tumor progression, metastasis and inflammation by site-specific cleavage of several adhesion molecules and cytokines." (PMID 29382156, 2018). "In oral squamous cell carcinoma, overexpression of ADAM10 associates with αvβ6 mediated invasiveness of the tumor cell." (PMID 28260841, 2017). "ADAM10 is also associated with tumor progression, metastasis and inflammation by site-specific cleavage of several adhesion molecules and cytokines." (PMID 28066176, 2016). "ADAM10-mediated N-cadherin shedding was associated with cancer cell migration promoting tumor progression and metastasis." (PMID 28066176, 2016). "In conclusion, the presence of anti-ADAM10 auto-Abs seems to reflect the increased tumor expression of the immunogenic immature-ADAM10 in a group of Crc patients, and is associated with a favourable prognosis in patients at stage III of the disease." (PMID 27517630, 2016). "ADAM10 is associated with tumor progression and confers resistance to doxorubicin-induced apoptosis in HCC cells by activation of the PI3-K/Akt pathway." (PMID 26514126, 2015). "Stromal exosomes taken from cells deficient in TIMPs, harbour bioactive enzymes such as ADAM10 that support the generation of myofibroblasts with classical traits of tumour promotion including heightened HGF, SDF1 and other factors." (PMID 25596732, 2015). "Interestingly, several fibrinogens were notably more abundant in ADAM10 KO tumours and are known to be associated with chondrogenic differentiation." (PMID 41226720, 2025). "However, the majority of significantly differentially expressed proteins in KO tumours were unique to tumours, underlining the impact of the tumour microenvironment on ADAM10 function." (PMID 41226720, 2025). "ADAM10 is overexpressed in many cancers and linked to tumor progression." (PMID 38667323, 2024).
tumor (continued). "Furthermore, our analysis revealed a clear association between the levels of ADAM10 expression and tumor size as well as histological grade." (PMID 39346916, 2024). "Moreover, the ADAM‐10 SNP rs653765 CT+TT was significantly associated with an OSCC tumour size larger than T2 in cigarette smoker (AOR: 1.346, 95% CI: 1.023–1.772, p = 0.034)." (PMID 36946281, 2023). "ADAM10 expression was associated with advanced tumor disease at RC." (PMID 33672843, 2021). "Interestingly, ADAM10 depletion was associated with decreased tumour progression as shown by biophotonic imaging measurements." (PMID 30651596, 2019). "The effect of ADAM10 on the biological behaviors of tumor cells may be associated with its protease activity." (PMID 25333745, 2015). "Combing the findings from our study and the TCGA database, it may be possible that the ADAM‐10 SNP rs653765 CT+TT variant trigger a larger tumour size of OSCC in smoker, but the expression of ADAM‐10 mRNA was down‐regulated by the presence of this genetic polymorphism and the cigarette smoking." (PMID 36946281, 2023). "Moreover, ADAM10 was linked with advanced tumor stage and positive lymph node status at RC." (PMID 33672843, 2021). "However, ADAM10 expression seems to be associated with advanced tumor disease." (PMID 33672843, 2021). "In our study, we could also show that expression of ADAM10, which is the principal sheddase in Notch signaling and regulates cell fate and differentiation, was associated with advanced tumor disease at RC, resulting in a higher incidence of positive pathological lymph node and extravesical disease." (PMID 33672843, 2021). "Moreover, ADAM10 has been found associated to exosome-like vesicles produced by Hodgkin lymphoma cells; thus, the activity of this protease might be spread in the tumor microenvironment, affecting the shedding process of NKG2D ligands and other substrates." (PMID 32269567, 2020). "In HR patients, the relative risk for tumor relapse is/was similar as for T patients, and in fact, some of the pEV characteristics were similar in both group, as, for example, the up-regulation of microRNAs not found in healthy controls and their content of active ADAM10." (PMID 30846484, 2019). "Indeed, anti-ADAM10 auto-Abs were associated with an impressive prolonged recurrence-free survival condition in the patients at stage III of the pathology when lymph nodes start to be infiltrated by the tumor cells." (PMID 27517630, 2016). "Growth of ADAM10 KO SW620 cells as tumours in mice was also significantly slower, compared to parental WT cells." (PMID 41226720, 2025). "Inhibition or knockdown of APP and ADAM10 reduced proliferation, supporting their roles in tumor progression." (PMID 41614805, 2025). "This suggested that ADAM10 function is particularly evident in the context of the tumour microenvironment (TME)." (PMID 41226720, 2025). "Future work incorporating both orthotopic and immunocompetent mouse models will be needed to further investigate the tumour-promoting roles of ADAM10 and its potential as a therapeutic target." (PMID 41226720, 2025). "Collagens and proteins associated with matrix deposition and fibril organisation were notably reduced in ADAM10 KO GBM tumours, and histology confirmed decreased collagen fibrils and blood vessels." (PMID 41226720, 2025). "Key GO functional protein sets that were modulated by ADAM10 also correlated with ADAM10 expression in human tumours, including proteins involved in cell–cell interaction, Notch signalling, angiogenesis, and ECM organisation." (PMID 41226720, 2025). "We also used label-free quantitative mass spectrometry to compare ADAM10 KO tumours to Wt U251 tumours taken at similar sizes (250–300 mm3), for unbiased identification of altered protein expression." (PMID 41226720, 2025).
tumor (continued). "Mechanistically, ADAM10-mediated shedding generates sGPNMB that drives tumor cell migration and invasion through MMP activation, while simultaneously shaping an immunosuppressive TME marked by M2 macrophage infiltration and CD44+ immune cell accumulation." (PMID 41180454, 2025). "The observed functional synergy between tRF-3021a, ADAM10, and sMICA suggests a coordinated axis that facilitates immune evasion and tumor growth, positioning tRF-3021a as a potential therapeutic target for disrupting this pathogenic cascade." (PMID 40726981, 2025). "Unexpectedly, increased chondrocyte differentiation was evident in ADAM10 KO U251 tumours, suggesting a role for ADAM10 in maintaining an undifferentiated phenotype in vivo." (PMID 41226720, 2025). "Together, our results indicate that ADAM10 regulates tumour development via diverse signalling pathways, promoting ECM reorganisation, tumour angiogenesis, and a more fibrotic phenotype." (PMID 41226720, 2025). "Consistent with this, our results show decreased Notch and increased chondrogenesis in ADAM10 KO tumours, in keeping with a more differentiated and less stem-like tumour phenotype." (PMID 41226720, 2025). "This indicated a decrease in fibrils in ADAM10 KO tumours, reflecting the reduced levels of collagens, the cross-linker LOXL3, and other ECM proteins identified above." (PMID 41226720, 2025). "In conclusion, sICOSL-blockade therapy, including EZH2 and ADAM10/17 inhibitors, enhanced T cell cytotoxicity, delayed tumor progression and enhanced tumors response to chemoimmunotherapy." (PMID 40708008, 2025). "In comparison to proliferation in vitro, growth of all ADAM10 KO U251 lines as tumours in mice was severely delayed, relative to wild type controls, being barely detectable after 6 weeks, when Wt tumours had begun to reach the ethical endpoint." (PMID 41226720, 2025). "In colon cancer, high levels of ADAM10, particularly a tumour-selective high-molecular-weight (unprocessed) form, are associated with advanced disease." (PMID 40427200, 2025). "Together, our data indicate the importance of ADAM10 in diverse signalling mechanisms in tumours and the TME that promote tumour development." (PMID 41226720, 2025). "Research on the HIF-1α/ADAM10 signaling pathway in tumor occurrence and development is relatively scarce." (PMID 40563539, 2025). "APMAP was mainly expressed in lymphocytes and cancer cell, SPI1 was highly expressed in macrophages, and ADAM10 showed high expression in cancer cell and lymphocytes, indicating their potential roles in tumor immunity and microenvironment regulation." (PMID 40396172, 2025). "We firstly confirmed the ADAM10 KO in tumours by immunoprecipitation from tumour extracts, using the human ADAM10-specific antibody 4A11 to differentiate ADAM10 in human tumour cells versus mouse cells of the host microenvironment." (PMID 41226720, 2025). "It consists of monomethyl auristatin E (MMAE) as the payload and a humanized IgG1 mAb (Hu2G10) that can selectively target ADAM10-activated Trop2 on transformed tumor cells." (PMID 38948057, 2024). "Considering the nature of cytoplasmic circRNAs in mediating gene regulation, we performed bioinformatic analyses and found that circSNX5 RNA potentially acts as a miRNA sponge, protecting ADAM10 from degradation by tumor suppressor miR-323a-5p." (PMID 39155279, 2024). "One example is enhancing miR-122’s tumor-suppressing action by targeting ADAM10, IGF1R, cdk G1, and ADAM17." (PMID 38915826, 2024). "Alberti's team identified the cleavage of Trop2 by ADAM metallopeptidase domain 10 (ADAM10) as a critical switch activating tumor growth and metastasis." (PMID 38948057, 2024). "The present study further revealed that ADAM10 was negatively associated with T cells CD4, T cells CD4 naive, macrophages, MHCs, AZs, monocytes, and other immune cells associated with tumor infiltration." (PMID 39211038, 2024).
tumor (continued). "Tumor-specific proteolytic cleavage of Trop2, induced by ADAM10 at R87-T88 of TY domain, demonstrated an activator switch for tumor growth and metastasis." (PMID 38179054, 2023). "ADAM10 is upregulated on dormant ALL cells and associated with poor clinical outcome; it is essential for AL homing to the BM, tumor growth, LSC maintenance and response to chemotherapy." (PMID 37422628, 2023). "DPAGT1-overexpressing SK-BR-3 tumors with ADAM10 KO showed a sensitive response to trastuzumab treatment, as indicated by significant shrinkage of tumor volumes." (PMID 37463446, 2023). "We discovered that activation of Trop-2 for induction of tumor progression requires proteolytic activation by ADAM10." (PMID 37509383, 2023). "Our data support adding ADAM10-targeting drugs to conventional therapeutic regimens in AL patients, at best upon tumor specificity to avoid adverse effects." (PMID 37422628, 2023). "We discovered that activation of Trop-2 as a driver of tumor progression requires proteolytic cleavage by ADAM10." (PMID 37509383, 2023). "In conclusions, the ADAM‐10 SNP rs2305421 G allele is associated with the presence of OSCC, and the ADAM‐10 SNP rs383902 TC+CC and ADAM‐10 SNP rs653765 CT+TT correlates to large tumour size in specific conditions." (PMID 36946281, 2023). "In the subgroup analysis, the presence of ADAM‐10 SNP rs383902 TC+CC was significantly correlated to an OSCC tumour size larger than T2 in betel quid chewer (AOR: 1.375, 95% CI: 1.010–1.872, p = 0.043)." (PMID 36946281, 2023). "An example of utilizing miRNA targets is the attempt of enhancing the tumor-suppressing effect of miR-122, which targets ADAM10, IGF1R, as well as cyclin G1 and ADAM17." (PMID 37108330, 2023). "Nine of these genes were involved in tumour progression in PCa including ADAM10, which enhances PCa metastasis." (PMID 37754243, 2023). "The authors also indicated a correlation between high mRNA expression of metalloproteinase ADAM10/17 in tumour cells and the concentration of sPD-L1 in peripheral blood." (PMID 37816808, 2023). "According to the literature, ADAM10 acts through both tumor cell intrinsic effects and bidirectional crosstalk of PDX AL models with the tumor microenvironment." (PMID 37422628, 2023). "In the first degree, a higher protein concentration of ADAM10 was demonstrated in the tissue of the surgical margin than in the tumor (282.78 vs. 203.5; p < 0.05)." (PMID 36286024, 2022). "In summary, we show evidence for conformation-specific binding of antibody 8C7 to ADAM10, and its tumour selectivity in mice, supporting development of 8C7-based ADCs." (PMID 35804938, 2022). "We thus set out to further define the selectivity of 8C7 for active ADAM10, and to investigate the potential of novel 8C7 antibody–drug conjugates (ADCs) for the selective delivery of cytotoxic drugs to tumours." (PMID 35804938, 2022). "Inhibition of ADAM17 expression by siRNA can increase the sensitivity of A549 cells to anti-tumor drugs; ADAM10 was overexpressed in A549 cells." (PMID 36606198, 2022). "While ADAM10 is ubiquitously expressed, its activity is normally tightly regulated, but becomes deregulated in tumours." (PMID 35804938, 2022). "This study provides the first demonstration that antibody–drug conjugates targeting an active conformer of ADAM10, a widely expressed transmembrane metalloprotease, enable tumour-selective targeting and inhibition." (PMID 35804938, 2022). "Accordingly, its higher expression in tumours correlates with poor patient prognosis for a range of tumour types, suggesting ADAM10 is a potential therapeutic target." (PMID 35804938, 2022). "In a DIPG xenograft mouse model, the ADAM10 inhibitors decreased tumor cell proliferation and subsequent tumor growth." (PMID 36357661, 2022). "In the study presented, we approached the expression of both ADAMs immunohistochemically and revealed a moderate to high ADAM17 and a distinctly weaker ADAM10 protein expression in RB patients’ tumor sections." (PMID 36293469, 2022).